APPBP2 (amyloid beta precursor protein binding protein 2)
Description:
Substrate-recognition component of a Cul2-RING (CRL2) E3 ubiquitin-protein ligase complex of the DesCEND (destruction via C-end degrons) pathway, which recognizes a C-degron located at the extreme C terminus of target proteins, leading to their ubiquitination and degradation. The C-degron recognized by the DesCEND pathway is usually a motif of less than ten residues and can be present in full-length proteins, truncated proteins or proteolytically cleaved forms. The CRL2(APPBP2) complex specifically recognizes proteins with a -Arg-Xaa-Xaa-Gly degron at the C-terminus, leading to their ubiquitination and degradation. The CRL2(APPBP2) complex mediates ubiquitination and degradation of truncated SELENOV selenoproteins produced by failed UGA/Sec decoding, which end with a -Arg-Xaa-Xaa-Gly degron. The CRL2(APPBP2) complex negatively regulates beige adipocyte differentiation by mediating ubiquitination and degradation of PRDM16 (By similarity). May play a role in intracellular protein transport: may be involved in the translocation of APP along microtubules toward the cell surface.
Synonyms: APP-BP2; KIAA0228; PAT1; Hs.84084
Tractability: Antibody: UniProt places it where antibodies can reach, with high confidence. PROTAC: ubiquitination databases record sites on it.
Gene: Protein-coding gene on chromosome 17 (60,443,158 to 60,526,242, reverse strand). Ensembl gene ENSG00000062725.
Subcellular location: Nucleus; Cytoplasm, cytoskeleton; Membrane
Subcellular location (Human Protein Atlas): Nucleoplasm
Gene Ontology:
Molecular function: protein binding; ubiquitin-like ligase-substrate adaptor activity; microtubule motor activity
Biological process: intracellular transport; proteasome-mediated ubiquitin-dependent protein catabolic process; ubiquitin-dependent protein catabolic process via the C-end degron rule pathway; intracellular protein transport; negative regulation of beige fat cell differentiation; protein ubiquitination
Cellular component: Cul2-RING ubiquitin ligase complex; cytoplasmic vesicle membrane; membrane; nucleoplasm; cytoplasm; microtubule associated complex; nucleus; cytoskeleton
Genetic constraint (gnomAD): Loss-of-function variants: 11 observed, 53.58 expected, observed/expected ratio (o/e) 0.21, 90% interval 0.13 to 0.34. The upper end of that interval is the gene's LOEUF score, 0.34, which puts it in group 1 of 6, group 1 being the genes least tolerant of losing a copy. Missense variants: 332 observed, 579.93 expected, observed/expected ratio (o/e) 0.57, 90% interval 0.52 to 0.63. Synonymous variants: 185 observed, 213.08 expected, observed/expected ratio (o/e) 0.87, 90% interval 0.77 to 0.98.
Homologues: Orthologues: chimpanzee APPBP2 (99% identical), macaque APPBP2 (99% identical), pig APPBP2 (99% identical), dog APPBP2 (99% identical), guinea pig APPBP2 (99% identical), mouse Appbp2 (99% identical), rabbit APPBP2 (99% identical), rat Appbp2 (99% identical), zebrafish appbp2 (93% identical), tropical clawed frog appbp2 (88% identical). Paralogues in human: KLC2 (20% identical), KLC1 (20% identical), KLC4 (20% identical), KLC3 (18% identical), NPHP3 (18% identical).
Diseases named in the same sentence as APPBP2 in open-access papers:
APPBP2 is named in the same sentence as 13 diseases in open-access papers, as found by Europe PMC text mining. Sharing a sentence is not in itself a finding about the gene and the disease. The quoted sentences say what the papers report.
breast carcinoma (3 papers, 2012 to 2022). "17, a region which included three genes: USP32 (ubiquitin specific peptidase 32), known to be overexpressed in breast cancer and colorectal metastatic disease, C17orf64 (an open reading frame) and APPBP2 (amyloid beta precursor protein binding protein 2), also highly expressed in breast cancer." (PMID 31795195, 2019). "Several of the genes involved are also in signalling pathways relevant to breast cancer: ERBB2, NRIP1 and BCAS3 are involved in estrogen receptor function and APPBP2 with androgen receptor; while TAOK1 and SKAP1 are involved in MAPK signalling and DEPDC6/DEPTOR regulates mTOR signalling." (PMID 23260012, 2012).
Insulin resistance (2 papers, 2022 to 2024). Increased resistance towards insulin, that is, diminished effectiveness of insulin in reducing blood glucose levels. "Adipocyte-specific deletion of Cul2 or Appbp2 counteracted diet-induced obesity, glucose intolerance, and insulin resistance while promoting adipocyte thermogenesis." (PMID 39351529, 2024).
non-small cell lung carcinoma (2 papers, 2010 to 2021). A group of at least three distinct histological types of lung cancer, including non-small cell squamous cell carcinoma, adenocarcinoma, and large cell carcinoma. "Silenced APPBP2 inhibited cell proliferation, migration and aggressiveness and enhanced apoptosis in non-small cell lung cancer." (PMID 34249502, 2021).
lung carcinoma (1 paper, 2022). "The orthologues were related to DHDH, ATP8B3, and P2RY1 genes, expressed in the lipid membrane, and directly related to skin and lung cancer genes (APP and APPBP2), suggesting that they may share mechanisms among these diseases." (PMID 36542226, 2022). "Additionally, APP interacted with Amyloid-Beta Precursor Protein Binding Protein 2 (APPBP2), which is involved in non-small cell lung cancer (NSCLC), a type of cancer accountable for ~ 80% of all lung carcinoma patients." (PMID 36542226, 2022).
tumour (3 papers, 2005 to 2007). "These include RPS6KB1, APPBP2, and PPM1D that also showed strong association between amplification and increased expression in our primary tumour material." (PMID 17353917, 2007). "Using a nondifferentially expressed control gene (APPBP2), cmRT–PCR was used to quantify the degree of relative AURKB expression between the normal and tumour tissues for each patient." (PMID 16222316, 2005).
APPBP2 also shares sentences with these, for which no sentence is quoted: cancer (3 papers); dyslipidaemia (2); Obesity (2); Alzheimer disease (1); brain tumors (1); breast tumours (1); Glucose intolerance (1); ovarian clear cell adenocarcinoma (1).